VIM (vimentin)
Diseases named in the same sentence as VIM in open-access papers (continued):
Sharing a sentence is not in itself a finding about the gene and the disease.
breast carcinoma (continued). "We demonstrated that ENTPD3 suppressed the expression of vimentin and promoted the expression of E-cadherin, suggesting that ENTPD3 inhibited breast cancer EMT." (PMID 31754326, 2019). "MTF efficiently decreases Vimentin, SNAIL and cell proliferation in mesenchymal breast cancer cells and also reverses IL-6-induced EMT by blocking STAT3 and NF-κB phosphorylation." (PMID 31337349, 2019). "Further, we found that knockdown RAI14 inhibits the proliferation, migration and invasion of breast cancer cells by regulating cell cycle and EMT through Akt/Cyclin D1, MMP2, MMP9 and ZEB1/E-cadhrin/Vimentin pathway." (PMID 31772666, 2019). "Western blotting results also confirm the elevated expression of E‐cadherin and the reduction in Vimentin and Twist1 expression, which is similar to the effect of MYOF in breast cancer cells." (PMID 29164766, 2018). "Vimentin expression was also shown to be transactivated by β-catenin/TCF, binding to a site upstream of vimentin promoter in breast cancer cells." (PMID 29925392, 2018). "Co-culture of breast cancer cells with MSC resulted in upregulation of EMT-specific markers (N-cadherin, vimentin, Twist, and Snail) and a decrease in E-cadherin." (PMID 30526687, 2018). "We then selected a BRCA1 mutant, ER-negative human breast cancer cell line, SUM149, in which p16 is deleted and VIM is expressed in 10–30% of total cells." (PMID 29996906, 2018). "In breast cancer cells, IFP was shown to promote the upregulation of Snail and vimentin, but also E-cadherin." (PMID 30487436, 2018). "In breast cancer cells repression of ZEB2, independently of ZEB1, resulted in reduced expression of a mesenchymal marker, Vimentin and reduced invasion." (PMID 29963231, 2018). "Immunoblot analyses revealed that BRC-31 breast cancer cells retained expression of EGFR, N-cadherin, fibronectin (FN) and vimentin at higher levels relative to BRC-32, 36 and 196 breast cancer cells." (PMID 29382358, 2018). "E: Immunofluorescence images for vimentin (green) and liprin-α1 (red) in MDA-MB-231 and Hs578T breast cancer cell lines and for vinculin (green) and liprin-α1 (red) in Hs578T breast cancer cell line after vimentin knockdown." (PMID 30005669, 2018). "Vimentin was considered to be a specific marker of EMT, which was highly expressed in various cancers including prostate cancer, breast cancer, malignant melanoma, lung cancer, and pancreatic cancer." (PMID 30249755, 2018). "Furthermore, high expression of EMT-induced markers (vimentin, α-smooth muscle actin (a-SMA), N-cadherin, cadherin 11, SpArC, laminin and fascin) with simultaneous low expression of E-cadherin has been associated with poor prognosis in patients with breast cancer." (PMID 30526687, 2018). "RT-PCR-based analysis of two EMT markers (Vimentin and Zo-1) in MDA-MB-231 breast cancer cell lines treated with Pimozide for 24 hours revealed a significant decrease in the RNA expression of both markers." (PMID 30405882, 2018). "A codelivery therapy that inhibits HMGA2 by siRNA and acts on DNA by doxorubicin showed efficacy in CRC and the same dual treatment inhibits cell growth, vimentin (stemness marker), and MMP9 (invasion marker) in breast cancer cells." (PMID 29853899, 2018). "The observation that BRC-31 breast cancer cells exhibit preferential ERK2 activation and express markers of an EMT transition (E-cadherin and cytokeratin-8 low; N-cadherin, FN and vimentin high) prompted us to examine the phosphorylation status of FRA-1." (PMID 29382358, 2018). "We found that the mean transcript expression of VIM, CDH2, FN1, and TWIST1 were higher in the basal B breast cancer cells with low FRK transcript levels as compared to Basal A and Luminal cells that harbor high FRK transcript levels (P<0.05)." (PMID 29348886, 2017). "In breast cancer cell lines, authors showed that the expression of CD151, VIM, and SNAI2 were suppressed, while CDH1 (an epithelial marker) was upregulated by miR-506." (PMID 28405738, 2017).
breast carcinoma (continued). "Consistently, IF analysis also revealed that β-lap significantly increased E-cadherin expression and decreased the expressions of Vimentin and MMP-9 in the MCF-7 and MDA-MB-231 breast cancer cell lines." (PMID 28578385, 2017). "Phenformin also dose-dependently upregulated mRNA levels of CDH1 with concomitant downregulation of VIM, SNAI1, and SNAI2, indicating that phenformin hinders EMT at the transcriptional level in breast cancer cells." (PMID 28947975, 2017). "In our study, we demonstrated that ectopic expression of AKR1B10 promoted breast cancer cell migration and invasion through activation of ERK signaling pathway and up-regulation of expression of MMP2, and vimentin." (PMID 28402270, 2017). "The propensity of breast cancer for metastatic dissemination is positively related to expression of Epithelial–Mesenchymal Transition (EMT) markers such as Twist1 and Vimentin, and negatively related to expression of adhesion markers such as E-Cadherin." (PMID 28978097, 2017). "The mean serum level of vimentin and DAKP1 in breast cancer patients below the age of 35 years was higher than patients aged 35 years and above." (PMID 28616237, 2017). "One report showed that breast cancer cells with MDR displayed enhanced metastatic activity, and they overexpressed N-cadherin, vimentin and the EMT-inducing transcription factors Slug, Twist and ZEB1/2." (PMID 28934275, 2017). "The serum concentrations of vimentin and DAPK1 were assessed in the serum samples of the breast cancer patients with respect to tumour grading." (PMID 28616237, 2017). "Specifically, miR-138 overexpression inhibits EMT process by targeting Vimentin and EZH2, thus reducing breast cancer invasion." (PMID 28606130, 2017). "In 3D breast cancer aggregates, elevated interstitial fluid pressure guided EMT shifting and collective cell invasion through Snail, vimentin and Ecad gene expression alterations." (PMID 28792442, 2017). "In this study, we found that fentanyl induced stemness and EMT in MCF-7 and MDA-MB-231 breast cancer cells by analysis of sphere formation, expression of stemness markers (Sox2, Oct4) and EMT markers (N-cadherin, E-cadherin and Vimentin)." (PMID 28798691, 2017). "In this study, we demonstrated that β-lap up-regulated epithelial marker E-cadherin, and down-regulated Vimentin, twist, Slug, Snail, and MMP-9, which indicated that β-lap suppressed EMT progression in breast cancer cells." (PMID 28578385, 2017). "It has been reported that knockdown of TRIM29 in breast cancer cells was sufficient to induce EMT with increased level of CDH2 and VIM and decreased level of CDH1 via suppression of TWIST." (PMID 29228692, 2017). "Co-implanting either type of MSCs with breast cancer cells increased primary tumor volumes and promoted the progression of the EMT, as shown by the presence of vimentin- or fibronectin-positive areas in primary tumors." (PMID 28761088, 2017). "In this study the serum levels of vimentin and DAPK1 were determined in archived sera of breast cancer patients and apparently healthy controls." (PMID 28616237, 2017). "Our current data showed that PTPRD downregulation significantly induced breast cancer cell EMT by promoting, in parallel with increased vimentin and decreased E-cadherin expression, their migratory and invasive capacities." (PMID 29228728, 2017). "In MDA-MB-231 breast cancer cells with liprin-α1 knockdown, vimentin cage structure was detected near the nucleus and in metastatic UT-SCC-24B HNSCC cells, vimentin accumulated as aggregates near the nucleus." (PMID 27075696, 2016). "To characterize the expression of AXL in vitro, we analyzed the expression of the tyrosine kinase, EMT (CDH1 and VIM), and basal (EGFR, KRT5, and KRT6A) markers in 15 breast cancer cell lines by quantitative real-time PCR (qRT-PCR)." (PMID 28721387, 2016).
breast carcinoma (continued). "PAC inhibited the migration/invasion abilities of breast cancer cells through inhibiting the ERK1/2 and AKT protein kinases, and repressed the mesenchymal markers vimentin and N-cadherin." (PMID 27465411, 2016). "Liprin-α1 knockdown led to vimentin accumulation near the nucleus in both of these cells as well as formation of vimentin bridges and multinucleated cells in both the HNSCC and breast cancer cell lines." (PMID 27075696, 2016). "Their system was based on the evaluation of vimentin, a classic mesenchymal marker, expressed in MDA-MB-231 breast carcinoma cell line in agarose/ECM-hydrogel 3D cell culture system." (PMID 27622654, 2016). "EGCG interacts with target proteins in the breast cancer cells, such as ERα, Zap-70, PI3K, G3BP1, IGF-1R, vimentin, Bcl-2, Bcl-xL, GRP78, and Fyn via hydrogen bonding, which plays a role in the inhibition of breast cancer." (PMID 27483305, 2016). "Western blot was used to compare the expression levels of E-cadherin, N-cadherin, and vimentin in breast cancer lines MCF-7 and MDA-MB-231, between PGCCs with budding daughter cells and control breast cancer cells." (PMID 26702618, 2015). "Co-expression of epithelial proteins, such as E-cadherin, and mesenchymal markers, such as vimentin, has been observed in the majority of circulating tumor cells (CTC) of metastatic prostate and breast cancer patients." (PMID 26068949, 2015). "Vimentin and Snail are two crucial molecules involved in EMT progression and have a vital role in breast cancer cell migration and invasion." (PMID 26540629, 2015). "In breast cancer patient samples, varying levels of ING1 expression were found in the stromal (vimentin positive) regions, which were quantified and then used for classifying patients with low stromal or high stromal ING1 expressing tumors." (PMID 26306560, 2015). "To clarify how vimentin contributed to EMT-related tumorigenesis and its role in cytoskeleton coordinated mechanotransduction, we performed different stages of breast cancer cells to evaluate EMT-induced tumorigenesis and mechanotransduction." (PMID 25965826, 2015). "As our focus was on the expression of ING1 protein in the stromal region of breast cancer patients, we used the expression of ING1 in the vimentin positive region of normal breast tissue sample as our baseline control." (PMID 26306560, 2015). "Exposure to 20 μM curcumin for 48 h decreased the expression of vimentin, increased the expression of E-cadherin, inhibited cell motility and invasiveness in MCF-7, MDA-MB-231 breast cancer cells exposed to lipopolysaccharide (LPS) in order to trigger EMT." (PMID 26694341, 2015). "Cluster I showed overexpression of the lncRNAs that influence their neighboring genes, ALDH1A3 (a breast cancer stem cell marker), SOX4, SOX9, and VIM." (PMID 25296969, 2014). "Further implicating EMT in CTC production, CTCs obtained from metastatic breast cancer patients express a much higher rate of Twist and vimentin, two markers of EMT, than patients with early breast cancer." (PMID 25566498, 2014). "Our experiments demonstrated that estrogen induced cellular morphological changes in breast cancer cells, consistent with the acquisition of the EMT phenotype, as characterized by the upregulation of vimentin and downregulation of E-cadherin expression." (PMID 24889938, 2014). "One objective of this study was to investigate the expression patterns of those clinically relevant biomarkers for breast cancer (ER, HER2, PI3K, vimentin and E-cadherin) in commonly used breast cancer cells." (PMID 24676558, 2014). "In breast cancer cells, the pharmacological inhibition of STAT3 activation using a small molecule inhibitor, Stattic, potentiated HNK-mediated inhibition of vimentin." (PMID 25405202, 2014). "In contrast, the highly invasive HNSCC cell line HN-12 and breast cancer cell line MDA-MB-231 were of more elongated, fibroblast-like mesenchymal appearance with reduced E-cadherin and increased Vimentin expression." (PMID 24885626, 2014).
breast carcinoma (continued). "miR-506 suppressed the expression of mesenchymal genes such as Vimentin, Snai2, and CD151 in MDA-MB-231 human breast cancer cell line." (PMID 23717581, 2013). "In this study, we observed that miR-506 played a role as a master suppressor of EMT in breast cancer through the direct targeting CD151, VIM and SNAI2." (PMID 23717581, 2013). "With the exception of breast carcinoma-derived MDA-MB-231 cells, IGF2BP1 expression was well correlated with the expression of the mesenchymal marker vimentin (VIM)." (PMID 23677615, 2013). "We therefore analyzed the expression of mesenchymal markers connected with EMT activation (VIM, TWIST1, SNAI1 and SNAI2) in PT, CTCs-EBF and LNM of breast cancer patients." (PMID 24217115, 2013). "In endocrine-sensitive luminal breast cancer cells, expression of miR-200 family members represses ZEB1, thus E-cadherin is expressed and vimentin is repressed and cells have an epithelial phenotype." (PMID 23626803, 2013). "Immunostaining of breast cancer patient CTCs revealed EMT markers Twist and vimentin in 73% and 77%, respectively, of CTCs from patients with early disease, and in 100% of the CTCs from patients with metastatic disease." (PMID 24240660, 2013). "We performed immunohistochemistry and immunofluorescence staining to determine vimentin+, c-kit/CD117+ and CD34+ TCs in EMT-6/stromal cells reconstituted breast cancer tissue." (PMID 23206234, 2013). "Vimentin and TGF-β regulates MTHFD2 (methylenetetrahydrofolate dehydrogenase 2) expression in metastatic breast cancer cells." (PMID 26237148, 2013). "Concordant with this phenotype, mRNA expression of epithelial E-cadherin and ZO1 was enhanced, whereas transcription of mesenchymal genes (N-cadherin, Vimentin, Fibronectin, MMP3) was reduced in TBX2-depleted MDA-MB-435 and MDA-MB-157 breast cancer cells." (PMID 22844464, 2012). "qRT-PCR, immunofluorescent assay and western blot was used to observe the variation of Vimentin and α-SMA in breast cancer cells." (PMID 22693547, 2012). "More recently, increased vimentin expression, indicative of EMT processes in CTCs in another orthotopic breast cancer model, has been published." (PMID 22591372, 2012). "Basal-like breast carcinomas have variable expressions of basal cytokeratins (CKs) (CK5/6, CK14, CK17), vimentin, myoepithelial markers (smooth muscle actin, p-63), CD117, P-cadherin and/or human EGFR (HER1/EGFR)." (PMID 23082819, 2012). "Twist and vimentin markers, suggesting EMT, were identified more often in patients with metastatic disease than in early-stage breast cancer." (PMID 22577580, 2012). "Consistent with the inhibition of invasion, CHD5 down-regulated mesenchymal markers vimentin, N-cadherin and ZEB1 in breast cancer cells." (PMID 22569290, 2012). "Elevating vimentin and α-SMA expression lead to a high metastasis potentiality and some mesenchymal cell characteristics in breast cancer cells." (PMID 22693547, 2012). "CTCs expressing Twist and vimentin, suggestive of EMT, are identified in patients with breast cancer." (PMID 21663619, 2011). "Recent studies have demonstrated that vimentin is expressed in DTCs of breast cancer patients and tumour cell lines; however, there have been no studies in which the expression of both EMT markers (Twist and vimentin) was evaluated in CTCs." (PMID 21663619, 2011). "Structural proteins reported to have increased expression in basal-like breast carcinomas include basal cytokeratins (CK5/6, CK14 and CK17), vimentin, fascin, nestin and moesin." (PMID 24281106, 2010). "WalBC cells exhibited expression of known markers of basal invasive human breast cancers as well as increased KRT17, KRT 14 and KRT 19, DSP, s100A4, NDRG-1, ANXA1, TK1 and AQP3 gene expression and decreased gene expression of TIMP3, VIM and TAGLN." (PMID 18179684, 2008).
breast carcinoma (continued). "Breast cancer cells treated with recombinant COMP or engineered to overexpress COMP exhibited a marked decrease in the epithelial marker CDH1 and an increase in mesenchymal markers such as VIM and VCAN." (PMID 41689303, 2026). "In patients with luminal A breast cancer, high expressions of BMP-4, SDF-1, and vimentin demonstrated a more substantial positive impact on overall survival (BMP-4 p = 0.0025; SDF-1 p = 0.0019; vimentin p = 0.00051)." (PMID 39859358, 2025). "The findings here reported suggest that vimentin, BMP-2, BMP-4, and SDF-1 could be independent prognostic biomarkers in breast cancer, providing insights beyond traditional clinical factors." (PMID 39859358, 2025). "Previous TMAs have allowed us to detect levels of mitotic kinases in breast cancer tissues of patients of different races and ethnicities and correlate their levels with pathologic subtypes of breast cancer (e.g., PR, ER, HER2, and Ki-67), as well as surrogate markers of metastasis (e.g., vimentin)." (PMID 40309949, 2025). "A similar effect was observed in breast cancer, where MA abolished the migration of cancer cells by influencing the EMT process through the elevation of E-Cadherin and the reduction of mesenchymal markers, Vimentin and Snail." (PMID 39863145, 2025). "Similarly, suppression of vimentin and ZEB1 occurred when lncRNA TUSC8 competed with miR-190b-5p, that consequently led to the inhibition of metastasis in breast cancer." (PMID 39912983, 2025). "In the investigation of breast cancer metastasis, numerous reports suggest that MCF‐7 cells serve as a model for low invasive epithelial cells, typically characterised by elevated levels of E‐cadherin and reduced levels of N‐cadherin, vimentin, and Snail." (PMID 40099939, 2025). "Specifically, in breast cancer, VIM has been shown to prevent miR‐dependent negative regulation of tissue factor mRNA by interacting with its 3′‐UTR during EMTs of circulating tumor cells, promoting coagulant activity associated with early metastasis." (PMID 39781570, 2025). "In breast cancer cells, NAT10 knockdown reversed docetaxel‐induced EMT and restored sensitivity to docetaxel, as evidenced by upregulated CDH1 (E‐cadherin) expression and downregulated VIM (vimentin) expression." (PMID 39764566, 2025). "Therefore, targeting vimentin and/or XIST via RNA interference should be a promising therapeutic strategy for breast cancer treatment." (PMID 40690373, 2025). "Similarly, TMEM97 silencing in breast cancer cell lines MCF-7 and MDA-MB-231 elevated E-cadherin protein levels but reduced N-cadherin and vimentin along with other classic EMT markers such as ZEB1, Twist, Snail, and Slug." (PMID 39995975, 2025). "Similar results were obtained in tramadol-treated MCF-7 cells; however, the authors did not detect vimentin in this type of breast cancer." (PMID 39861181, 2025). "Notably, approximately 70% of CTCs in both metastatic colorectal and breast cancers express the epithelial cell adhesion molecule (EPCAM), members of the Keratin (KRT) family, and/or vimentin (VIM)." (PMID 40565003, 2025). "In a study, VISTA expression in breast cancer shows a negative correlation with the epithelial marker E Cadherin and a positive correlation with mesenchymal genes (Vimentin, Slug and Zeb1)." (PMID 40344465, 2025). "They showed that partial EMT, which is marked by low E-cadherin expression and high vimentin expression, combined with decreased matrix stiffness, can lead to the explosive (burst-like) movement of human breast cancer cells and non-cancerous cells." (PMID 40643464, 2025). "Furthermore, in breast cancer cell lines MCF-7 and MDA-MB-231, shRNA-mediated depletion of TET1 or TET3 would reduce the expression of mesenchymal genes N-cadherin and vimentin during hypoxia." (PMID 40764968, 2025). "It was found that the lower the expression of VIM, the longer the survival period of breast cancer patients, indicating a negative correlation between the two." (PMID 39781570, 2025).